MMP9 (matrix metallopeptidase 9)
Diseases named in the same sentence as MMP9 in open-access papers (continued):
Sharing a sentence is not in itself a finding about the gene and the disease.
breast carcinoma (continued). "MMP2 and MMP9 expression is known to be highly upregulated in almost every metastatic cancer cell type, and elevated MMP9 level is associated with the high potential of metastasis in several human carcinomas, including breast cancer." (PMID 32708426, 2020). "Up-regulation of VEGFR1 and MMP9 expression by tumor-derived exosomes was linked with breast cancer metastasis and extracellular proteolysis and angiogenesis, respectively." (PMID 31555295, 2019). "The overexpression of MMP-9 is associated with higher rates of metastasis, shorter recurrence latency, and shorter post-recurrence survival as well as with breast cancer invasiveness." (PMID 31514467, 2019). "Compared with normal tissues, breast cancer tissues have higher expression levels of MMP-9, which suggests it is associated with breast cancer development and tumor progression." (PMID 31010242, 2019). "Further mechanistic details that came to light centered on NF-kB site on the MMP9 promoter that facilitated its up-regulation, providing a new mechanism underlying the invasiveness of breast cancer." (PMID 31346317, 2019). "Recent studies have established the anti-angiogenic effects of CuB associated with inhibition of VEGF/FAK/MMP-9 signaling in highly metastatic breast cancer cells." (PMID 31600949, 2019). "Studies have showed that concentrations of MMP-2 and MMP-9 are increased in women with breast cancer, and are associated with an unfavorable prognosis." (PMID 31839881, 2019). "Another recent study investigated the possibility of utilizing MMP-9 and RhoA level for breast cancer risk assessment through patient stratification." (PMID 30262739, 2018). "Our data is in concordance with these finding as we found a significant association between FoxM1 overexpression and VEGF and MMP-9 in our cohort of breast cancer cases." (PMID 29707121, 2018). "Further, low MMP-2 and MMP-9 mRNA levels are associated with better overall survival for breast cancer patients." (PMID 29874869, 2018). "Our objective was to evaluate the relationship between the MMP-9-1562 C/T polymorphism (rs 3918242) and the risk of developing breast cancer." (PMID 30352460, 2018). "In this clinical, cross-sectional case-control study, we evaluated the potential relationship of the MMP-9 gene polymorphism with breast cancer and aggressiveness of the disease." (PMID 30352460, 2018). "In the breast cancer cases from our hospital, high MMP-9 expression was significantly associated with high histological grade." (PMID 30142200, 2018). "Our study aims to shed light on genes associated with high MMP-9 expression and to discuss their clinical impact in breast cancer." (PMID 30142200, 2018). "An Iranian study, published in 2015, found association between higher risk of developing breast cancer and MMP-9 polymorphism, as the presence of mutant allele increased the susceptibility to the disease by 1.87 times (OR = 1.87, IC95: 1.05–3.33, p = 0.035)." (PMID 30352460, 2018). "MMP8 and MMP9 have been shown to be associated with breast cancer (BC) risk in European and American populations." (PMID 30194384, 2018). "The interaction dendrogram also further confirmed that MMP-1607 1G/2G and MMP3–1171 5A/6A SNPs have strong correlation whereas, MMP9-1562 C/T polymorphism has an additive effect on the risk of breast cancer development." (PMID 28961241, 2017). "Recently, one study showed that high expression levels of MMP9 and IGFBPs were associated with poor prognosis in patients with breast cancer." (PMID 28143425, 2017). "In contrast, high expression of IGFBPs was associated with a favorable prognosis in patients with breast cancer when MMP9 was expressed at low levels." (PMID 28143425, 2017). "The interaction information analysis revealed moderate effect between the markers -1607 1G/2G of MMP1, -1171 5A/6A of MMP3 and -1562 C/T of MMP9 genes which were conferring risk towards the progression of the breast cancer." (PMID 28961241, 2017).
breast carcinoma (continued). "MMP-8 appears to downregulate the TGF-β signalling evident in DCIS-associated MEC, and opposes MMP-9 activity, which we show promotes breast cancer cell invasion and also has been shown to prevent HD formation." (PMID 28330493, 2017). "Association of the MMP1–1607 1G>2G, MMP3-1171 5A>6A and MMP9-1562 C>T genotypes with breast cancer susceptibility and clinicopathological characteristics." (PMID 28961241, 2017). "Somiari and colleagues were able to detect elevated levels and activity of MMP-2 and MMP-9 in plasma from breast cancer patients, as well as in women determined to be high risk based on Gail Model predictions." (PMID 28228690, 2017). "With respect to MMP9–1562 C/T promoter polymorphism, our study revealed that the frequency of T-allele was found to be predominant in breast cancer group compared to controls, with a 1.44 folds increased risk for BC." (PMID 28961241, 2017). "In conclusion, our results suggest that MMP1–1607 1G/2G, MMP3–1171 5A/6A and MMP9–1562 C/T gene polymorphisms have strong correlation with breast cancer." (PMID 28961241, 2017). "Our results suggest that MMP1–1607 1G/2G, MMP3–1171 5A/6A and MMP9–1562 C/T gene polymorphisms have synergistic effect on breast cancer." (PMID 28961241, 2017). "In the present study SNPs of MMP1, MMP3 and MMP9 genes were correlated with clinicopathological features for their association in breast cancer progression and susceptibility." (PMID 28961241, 2017). "Genotype and allele frequencies distribution for MMP-1, MMP-3 and MMP-9 gene polymorphisms in controls and breast cancer subjects." (PMID 28961241, 2017). "As a consequence, increased expression of MMP2 and MMP9 have been associated with a more aggressive phenotype and poor prognosis in several solid tumors including breast cancer, ovarian carcinoma, head and neck squamous cell carcinoma and gastric cancer." (PMID 26979530, 2016). "High serum MMP-9 has been associated with poor disease-free survival and OS in previous studies in breast cancer patients." (PMID 27387327, 2016). "Aberrant activation of NF-κB is known to be associated with the progression of breast cancer, particularly the promotion of tumor cell invasion, migration, and metastasis through the upregulation of MMP-9 expression." (PMID 27776550, 2016). "MMP9 was found by others to be implicated in promoting breast cancer cell migration and invasion through interactions with integrins and non-integrin type receptors such as CD44." (PMID 27042827, 2016). "A weak association also was found between MMP9 expression and tumor angiogenesis in breast carcinoma." (PMID 27034751, 2016). "Aberrant MMP-2 and MMP-9 expression is apparent in breast cancers and these proteins release often associated with tumor invasion and metastasis." (PMID 26637807, 2016). "Previous findings indicated that the overexpression of MMP-9 in breast cancer tissues was significantly associated with LNM." (PMID 26656588, 2015). "Taken together, this work identified the TSP50 activation of MMP9 as a novel signaling mechanism underlying human breast cancer invasion and metastasis." (PMID 25811800, 2015). "The expression association between CD147 and MMP-2, MMP-9 has been well established in a series of human malignant tumors, such as gallbladder carcinoma, thyroid carcinoma, breast cancer, gastric cancer and colorectal cancer." (PMID 26507719, 2015). "Elevated levels of MMP9 expression is also associated with shortened relapse-free survival in breast cancer patients and a high rate of distant metastases." (PMID 25605249, 2015). "MMP9 is an important mediator of tumor invasion and angiogenesis, and is significantly associated with high breast cancer metastasis and relapse." (PMID 26084289, 2015). "Matrix metalloproteinase 2 and 9 (MMP-2 and MMP-9) have been implicated as playing significant roles in enabling invasiveness and metastasis of breast cancer." (PMID 25885600, 2015).
breast carcinoma (continued). "In particular, the proteolytic activity of MMP9 promotes loss of tissue polarity and induces proliferation and tumor growth of human breast cancer cells in a mouse xenograft model." (PMID 25901736, 2015). "a2Neuɸ secret increased levels of MMP-9; a protease mediating extracellular matrix remodeling which is associated with breast cancer metastasis." (PMID 26460736, 2015). "Accordingly, an increased collagenase IV (MMP2, MMP9) activity has been linked to high tumor grades in breast cancer specimen and poor prognosis." (PMID 26674091, 2015). "Despite the fact that oleic and linoleic acids induce MMP-9 release in breast cancer cells and bovine neutrophils, the mechanisms underlying this response are not well understood." (PMID 25790461, 2015). "In this study, we investigated how glaucine treatment affected MMP-9 expression in breast cancer cells and explored the underlying upstream signaling mechanisms." (PMID 25670016, 2015). "Nevertheless our results have demonstrated that directly targeting and decreasing expression of PRMT7 causes reduced MMP9 expression, which specifically in breast cancer, is a therapeutically advantageous effect." (PMID 25605249, 2015). "In particular, MMP-9 overexpression has been associated with the progression and invasion of different types of tumors, including mammary tumors." (PMID 25670016, 2015). "Elevated serum MMP-9 level was also associated with reduced disease-free survival (DFS) of breast cancer." (PMID 24476461, 2014). "An N-cadherin/FGFR/gelatinase B/MMP-9 axis has been implicated in breast cancer cell invasion and metastasis, bypassing E-cadherin invasion and metastasis suppressing signals." (PMID 24473089, 2014). "In summary, our results indicate that overexpression of MMP-9 is closely associated with breast cancers of high histological grade including triple-negative and HER2-positive molecular subtypes." (PMID 25151367, 2014). "Mutation at the MMP9 cleavage site in galectin-3 reduces extracellular galectin-3 and also suppresses tumorigenicity of breast cancer cells." (PMID 25499743, 2014). "An enhanced expression of MMPs, particularly the gelatinase (MMP-2 and MMP-9), is associated with high metastasis potential in several types of human carcinomas including breast cancer." (PMID 24618693, 2014). "Gelatinase B/MMP-9 interaction with CD44 also promotes breast cancer cell migration and invasion in association with EGFR activation." (PMID 24473089, 2014). "Among all MMPs, upregulation of MMP-2 and MMP-9 was shown to be associated with breast cancer metastasis and poor clinical outcome." (PMID 23874773, 2013). "Previous studies have demonstrated that the expression of matrix metalloproteinase-9 (MMP-9) has been associated with a high potential of metastasis in several human carcinomas including breast cancer." (PMID 24130769, 2013). "MMP9 activity has been implicated in breast cancer cell migration and ERK1/2 activity has been positively associated with increased MMP activity." (PMID 23727359, 2013). "In breast cancer, high expression levels of MMP-9 have been associated with node metastasis and advanced tumor stage." (PMID 23326564, 2013). "Our study is the only one to date to find an association between the coding SNP rs17576 in MMP9 and breast cancer risk." (PMID 23634849, 2013). "In agreement, we here provide evidence that although WNT‐5A activates Cdc42, it causes a downstream decrease in ERK1/2 and MMP9 activities those results in impaired breast cancer cell migration and invasion." (PMID 23727359, 2013). "Mmp9 contributes to mammary cancer metastasis in mouse models and nucleotide variants within MMP9 have been associated with breast cancer metastasis in humans." (PMID 24304664, 2013). "MMP3 and MMP9 were associated with breast cancer risk among those with most Native American ancestry and those with ER−/PR− tumors." (PMID 23696797, 2013).
breast carcinoma (continued). "Although no GWAS studies have found SNPs in MMP9 to affect breast cancer risk, many prior studies have published results that support an association between MMP9 and breast cancer risk." (PMID 23634849, 2013). "In breast cancer, only one study has reported the positive association between the serum level of lipocalin-2/MMP-9 complex and disease status." (PMID 22640376, 2012). "Serum MMP9 levels have also been shown to be significantly associated with breast cancer stage and size, gastric cancer stage, stromal reaction in gastric cancer, and CRC stage." (PMID 22433968, 2012). "Elevated lipocalin-2 and MMP-9 levels were associated with reduced DFS of breast cancer ( Ptrend = 0.029 and Ptrend = 0.063, respectively)." (PMID 22640376, 2012). "Our study suggests that the elevated levels of lipocalin-2 and MMP-9 are associated with reduced breast cancer survival, particularly in patients with lower BMI and lymph-node negative breast cancers." (PMID 22640376, 2012). "We show for the first time that Kp-10 stimulates breast cancer cell invasion concomitant with MMP-9 secretion and activity, and have implicated β-arrestin 2 in this process." (PMID 21738726, 2011). "A splice variant of CD99 increases motility and MMP-9 expression of human breast cancer cells, in osteosarcoma and prostate cancer." (PMID 20175889, 2010). "There is evidence about the regulation of the MMP-9 mRNA stability by α3β1 integrin, among others, that is associated with mammary carcinoma cell metastasis and invasion." (PMID 20942921, 2010). "Several proteases are implied in oncogenesis; among them members of the family of Metalloproteinases (MMP) are up modulated in neoplastic stroma; In particular, over expression of MMP-9 is associated with malignancy and poor prognosis in breast cancer." (PMID 19226458, 2009). "In this respect, a correlation between a high expression of MMP-2 and reduced survival in breast cancer patients as well as an association of the tumor grade with increased levels of MMP-9 in breast cancer tissue was described." (PMID 19531263, 2009). "Elevated levels of both MMP2 and MMP9 have been observed in blood from breast cancer patients and were repeatedly found to be associated with advanced stage, lymph node metastasis and poor prognosis." (PMID 18366705, 2008). "Several studies have evaluated the diagnostic and prognostic value of circulating MMP2 and MMP9 in breast cancer because of their important role in tumour invasion and metastasis." (PMID 18366705, 2008). "Surface association of CD44 with MMP-9 was shown to provide a mechanism for tumor invasion in mouse mammary carcinoma and human melanoma cells." (PMID 17343740, 2007). "Active MMP-9 has been found in association with the vCD44 isoform on the invadopodia of breast cancer cells." (PMID 17343740, 2007). "Several MMPs, in particular the gelatinases MMP-2 and MMP-9, have been recently studied as prognostic factors in breast cancer, being associated with a poor outcome in various subsets of patients." (PMID 17848954, 2007). "The expression of MMPs, particularly the gelatinases (MMP-2 and MMP-9) have been associated with high potential of metastasis in several human carcinomas including breast cancer." (PMID 16831226, 2006). "MMP-9 has been found to be associated with poor prognosis and metastatic potential of breast carcinoma." (PMID 16880790, 2006). "MMP2 and MMP9 have thus been potentially linked to breast cancer cell invasion and metastasis." (PMID 40735254, 2025). "Moreover, since the five proteins CD9, CD24, CD63, CD81, and MMP9 are universal and present in exosomes secreted by both primary endotheliocytes and breast carcinoma cells, they cannot be part of the diagnostic panels being developed." (PMID 40310419, 2025). "Our results conclude that MMP2 (rs2285053) is associated with an increased risk of breast cancer, while MMP9 (rs3787268) polymorphisms may be correlated with a reduced risk of breast cancer in Bangladeshi females." (PMID 40735254, 2025).
breast carcinoma (continued). "The current study concludes that MMP2 (rs2285053) is associated with an increased risk of breast cancer, while MMP9 (rs3787268) polymorphisms may be correlated with a reduced risk of breast cancer in Bangladeshi females." (PMID 40735254, 2025). "Slattery and colleagues suggested that Native American females are more likely to develop breast cancer if they carry the G to A variant of MMP9 rs3787268 and found that the GA and AA genotypes of rs3787268 were significantly associated with a 1.52‐fold risk of breast cancer in the same population." (PMID 40735254, 2025). "Particularly, gelatinases MMP2 and MMP9 appear highly expressed in breast cancer tissues and are strongly associated with tumor staging and metastasis, particularly driving TNBC metastasis, thereby serving as important biomarkers for assessing prognosis and guiding treatment strategies." (PMID 41228316, 2025). "Therefore, our study aimed to investigate the association between MMP2 (rs2285053) and MMP9 (rs3787268) gene polymorphisms with breast cancer in Bangladeshi females." (PMID 40735254, 2025). "Our findings suggest that higher levels of PAI-1 and MMP-9 in patients with early-stage breast cancer may be associated with a subgroup of patients with more aggressive disease progression." (PMID 40266038, 2025). "MMP-9 is highly induced in a wide range of malignancies and is often linked to increased invasiveness and/or metastasis in gliomas and skin tumors as well as colorectal, cervical, gastric, pancreatic, and breast cancers." (PMID 38801618, 2024). "Importantly, we also observed that the accumulation of CRP2 in the nucleus of breast cancer cells is associated with an increase in the expression of MMP-9 and MMP-13 transcripts." (PMID 37266453, 2023). "Another study revealed that MMP-9 polymorphism has an important role in breast cancer and may help to identify individuals with high risk." (PMID 37569509, 2023). "In addition to a prognostic value, MMP-9 is associated with the presence of circulating tumor cells (CTC) during early-stage breast cancer." (PMID 37372062, 2023). "Recent studies have linked the elevated MMP9 enzyme levels with poor prognosis in breast cancer patients, thus establishing an interesting correlation between the Hv1 channel upregulation, high levels of MMP9 expression in the breast cancer TME and poor survival in breast cancer patients." (PMID 37153807, 2023). "MMP-9 mRNA expression is associated with breast tumor tissue compared to normal tissue obtained from GEPIA analysis indicated that expression of MMP-9 was significantly higher in breast cancer than in normal tissues." (PMID 35538133, 2022). "MMP-9 has been shown to be associated with CD44 on breast cancer cells and human melanoma cells." (PMID 35264209, 2022). "In this study, administration of sinomenine can effectively repress hypoxia-caused VM formation and migration of breast cancer SP cells, with the downregulation of VE-cadherin, MMP-9, and EphA2, which are all closely related to VM formation and metastasis of cancer cells." (PMID 35309179, 2022). "YKL-40 expressed in breast cancer cells could promote the synthesis and secretion of MMP-9 by tumour associated macrophages, thus enhancing the invasiveness of breast cancer." (PMID 34259106, 2021).